FGFR2 (fibroblast growth factor receptor 2)
Diseases named in the same sentence as FGFR2 in open-access papers (continued):
Sharing a sentence is not in itself a finding about the gene and the disease.
tumor (continued). "FGFR2+ functional CAFs, which have differentiated in ESCC, can be mobilized by tumor-secreted FGF2 and recruited to the tumor site through the CXCL12–CXCR4 axis." (PMID 40134607, 2025). "This highly selective targeting of FGFR2 and FGFR3 translates into superior efficacy and improved tolerability in genetically defined tumor subtypes." (PMID 41514604, 2025). "FGFR2+ tumors also demonstrated separation between both CD4+ T cells and CD8+ T cells and tumor cells as compared to both IDH1+ iCCA and FGFR2 WT/IDH1 WT (p<0.001)." (PMID 39969434, 2025). "Aberrant activation of FGFR2 in GISTs, driven primarily by gene fusions (e.g., FGFR2::TACC2) and amplifications, triggers key oncogenic signaling pathways that promote tumor cell proliferation, survival, and resistance to TKIs." (PMID 41150770, 2025). "To summarize, the presented tumor is a CCMNs with involvement of the TMJ region and FN1::FGFR2 fusion." (PMID 39404883, 2025). "The combination of PD-1 inhibitors with FGFR2 inhibitors or IDH1 inhibitors aims to enhance immune responses and overcome tumour resistance mechanisms." (PMID 40861435, 2025). "Spatial relationships between polymorphonuclear myeloid-derived suppressor cells and multiple other cell types in the tumor microenvironment (including tumor cells, CD4+, and CD8+ T cells) were enriched in tumors with FGFR2 alterations." (PMID 39969434, 2025). "Mechanistically, SFRP1 from CFD+ iCAFs binds FGFR2, activating the HIF1 signaling pathway to enhance tumor stemness, EMT, and CRLM progression." (PMID 40225580, 2025). "The distance between CD11b+/CD15+ granulocytes and tumor cells, as well as both CD8+ and CD4+ T-cell subsets, was reduced as compared to IDH1+ iCCA and FGFR2 WT/IDH1 WT iCCA (p<0.001 for all comparisons)." (PMID 39969434, 2025). "•The importance of tumor molecular profiling and pemigatinib efficacy in CCA with FGFR2 fusions/rearrangements are described." (PMID 38838500, 2024). "Given that clinical evaluation of FGFR2 targeted therapy is underway, we sought to elucidate the genomic landscape of FGFR2amp in gastroesophageal cancer (GEC) using a circulating tumor DNA (ctDNA) platform." (PMID 38902956, 2024). "This agent demonstrated encouraging clinical activity in a first-in-human study involving 35 patients with FGFR2-altered CCA, with >10% tumor shrinkage observed in 56% of patients with CCA previously treated with an FGFR inhibitor." (PMID 39766138, 2024). "The Spearman correlation coefficients are as follows: NOTCH1 and FGFR2 expression, 0.988; NOTCH1 expression and tumor progression, 0.953; and FGFR2 expression and tumor progression, 0.953." (PMID 39063983, 2024). "Analysis of the TCGA database in TNBC samples revealed a correlation between the mRNA expression of FGFR1, FGFR2, and FGF2 and the hypomethylation status of tumour cells." (PMID 40135140, 2024). "Lenvatinib prevents tumor angiogenesis through inhibition of VEGFR-1, -2, and -3, and also blocks the proliferation of tumor cells through inhibition of FGFR-1, FGFR-2, FGFR-3, & FGFR-4, PDGFRα, RET, and c-KIT." (PMID 38622735, 2024). "There was also an interesting finding with the tumour type, with the more aggressive IDC having a lower FGFR2 expression than ILC; patients who had both ILC/IDC components to their carcinomas had FGFR2 levels between IDC alone and ILC alone." (PMID 39596875, 2024). "The Pearson correlation coefficients are as follows: NOTCH1 and FGFR2 expression, 0.988; NOTCH1 expression and tumor progression, 0.950; and FGFR2 expression and tumor progression, 0.948." (PMID 39063983, 2024). "FGFR2 fusion partners reported to date in GC include TACC2, INPP5F, WDR11 and BTBD16, and in most cases, these tumours harboured concurrent FGFR2 gene amplification." (PMID 38791079, 2024). "E7090 has been shown in NCT04238715 Phase II to have strong anti-tumor efficacy (ORR of 30%; DCR of 79%) and to be safe and controlled in the treatment of CCA patients with FGFR2 gene fusion." (PMID 38831455, 2024).
tumor (continued). "A biopsy revealed an FGFR2-INA fusion, and he was offered off-label pemigatinib and experienced a decrease in tumor size with ongoing disease control for 20 months." (PMID 39289482, 2024). "The results of a correlation analysis suggested that the number of tumor-infiltrating N1 neutrophils was high (P < .001) and that the number of N2 neutrophils was low (P < .001) in ICC patients with an FGFR2 fusion/rearrangement." (PMID 38986528, 2024). "We detected expression of FGFR1 and FGFR2 in tumor organoids, with higher levels in embryonal than fetal organoids, while FGFR4 was exclusively expressed in fetal tumor organoids." (PMID 39567475, 2024). "We present a case of a primary high-grade serous tubo-ovarian carcinoma with a novel FGFR2::IQCG fusion, an exceedingly rare combination of tumor type and fusion class, with an unusually short-lived response to futibatinib." (PMID 39759134, 2024). "Genetic testing revealed FGFR2-TXLNG-fusion, and the patient was treated with pemigatinib in combination with tislelizumab and SBRT for the BM, resulting in significant tumor shrinkage." (PMID 39697545, 2024). "We have responded to these weaknesses with additional methods (whole-tumor block analyses and multi-spot TMA) and believe that we have contributed valid data on FGFR2 heterogeneity." (PMID 36416959, 2023). "Fibroblast growth factor receptors (FGFRs) comprising FGFR1,FGFR2,FGFR3 and FGFR4 have been reported to play important roles in the regulation of the main target genes of lenvatinib and control tumour metabolism in many cancer types including HCC." (PMID 37846441, 2023). "To further validate differences in FGFR1 and FGFR2 expression within GBM, we identified publicly available RNA-seq datasets that compared tumor core versus infiltrating regions." (PMID 37579831, 2023). "Two of the five patients who had FGFR2 amplification in the primary tumor and metastasis on single-spot TMA were also analyzed with whole tumor blocks and, as expected, showed the same result." (PMID 36416959, 2023). "Activation of the FGFR2/STAT3 pathway promotes proliferation, invasion, migration, and EMT of tumor cells." (PMID 37750089, 2023). "These genomic differences may play a role not only in tumor location but also in therapeutic response: most of the ongoing phase III clinical trials on therapeutic strategies for iCCA are testing specific agents targeting IDH-mutated CCA (NCT02989857) and FGFR2 fusion-positive CCA (NCT03773302)." (PMID 36766711, 2023). "FGFR2 is upregulated in tumor epithelial cells, while FGF20 is increased in neighbor FAP(+) CAFs at EOCC tumor invasive margin." (PMID 37964075, 2023). "In this tumor type, CDK6 and FGFR2 were less expressed than in normal tissue, whereas CDK7, MET, ALK and AURKB stood out as upregulated in tumor samples." (PMID 36839989, 2023). "Another study showed that either Fgfr1, Fgfr2, or Fgfr3 gene knockout impeded SS18-SSX2-induced tumour formation in vivo and FGFR inhibitor (BGJ398) treatment reduced SS tumour cell growth in vitro and in vivo." (PMID 37130917, 2023). "We next evaluated the expression patterns of FGFR2 in GBM xenografts, again focusing on potential differences between the tumor core and the invasive edge." (PMID 37579831, 2023). "To identify gene regulatory networks related to FGFR1-driven GBM tumor invasion, we compared transcriptomes of control, FGFR1 knockdown, and FGFR2 knockdown GBM cells using RNA-Seq." (PMID 37579831, 2023). "We quantify relative expression levels of FGFR1 and FGFR2 in GBM patient-derived xenograft models and compare expression within the tumor core and the invasion front." (PMID 37579831, 2023).
tumor (continued). "Previous studies have shown the dynamic changes in the alterative splicing of FGFR2-IIIb/IIIc in the cellular transformation during EMT, and its importance in carcinogenesis and tumor metastasis in a variety of cancers." (PMID 37090731, 2023). "Our study suggests that a possible mechanism by which TAX represses the proliferation and tumor growth of androgen-independent PCa cells through down-regulating PI3K/AKT signaling pathway and the expression of FGFR2." (PMID 37567936, 2023). "Here, FGFR2 and ITGB1 expression levels were both significantly decreased in tumour samples (log2FC=-0.78, p = 0.006, and log2FC=-0.54, p < 0.00001, respectively)." (PMID 37191822, 2023). "In HB non-tumor and tumor regions, similar level of expression of CEBPB and FGFR2 were localized at the liver parenchyma." (PMID 36996081, 2023). "FGFR2 and its isoform are highly expressed in CRC and, as a result, are correlated with tumor oncogenesis, metastasis and angiogenesis." (PMID 37893023, 2023). "In summary, our study demonstrates differential expression of FGFR1 and FGFR2 on invasive GBM cells and provides functional and transcriptomic evidence that FGFR1 regulates tumor invasion in GBM." (PMID 37579831, 2023). "In addition, the finding that SCFAs attenuate Ras signaling in vivo, in part, by up-regulating the expression of human disabled 2 (DAB2), a tumor suppressor of the Ras and Wnt pathways, suggests that SCFAs may also impact FGFR2 and Hippo signaling in tumor development." (PMID 37432606, 2023). "While numerous fusion partners have been described for both FGFR2/3, one of the most common fusion partners with FGFR3 across multiple tumor types is transforming acidic coiled-coil-containing protein 3 (TACC3)." (PMID 37980380, 2023). "Primary human T-ALL cells with HS-5 were injected subcutaneously and BGJ398 or PBS was intraperitoneal injected every 2 days for a total of seven times, the growth of tumours in mice with FGF2 and FGFR2 blockade was slower than control mice (p < 0.05)." (PMID 36333298, 2022). "FGFR2 and FGFR3 mRNA expression varied between tumor and tumor-adjacent normal tissues and were enhanced 2–10 times in several tumor samples." (PMID 36142417, 2022). "Heterogeneity in HER2 and fibroblast growth factor receptor 2 (FGFR2) overexpressing cells in fresh tumour tissue was shown to be retained in PDOs, although differences in HER2 expression between primary tumour and PDOs have been reported as well." (PMID 35328567, 2022). "This is the first study to concurrently investigate the protein expression status of FGFR2 and HER2 in human tumor tissue from patients with CRC." (PMID 35585358, 2022). "Molecular targets for drug therapy have been evaluated for GC-PDX, and results showed that expression of the genes FGFR2, MET and HER2 in GC PDXs is representative of the original patient tumour." (PMID 35328567, 2022). "We found that 3.8% of top down-regulated DEGs in GKO tumours were CBX7 targets, including Wnt10a, CCNE1, FGFR2, and DUSP4." (PMID 35867177, 2022). "Recently, we have found that the activation of FGFR2 induces TNBC with multiple signaling, such as cancer stem cells (CSCs), epithelial–mesenchymal transition (EMT), and the tumor microenvironment (TME)." (PMID 35547739, 2022). "Crizotinib and AZD4547 exerted a significant anti-tumor effect only in PDX models with cMet (G30, G31) and FGFR2 (G03) amplification." (PMID 35664756, 2022). "Here, we systematically characterized the interaction process between tumor and FGFR2+ CAFs in ESCC, including how CAF progenitors were mobilized from BM, recruited into tumor sites and differentiated into functional CAFs by cancer cells." (PMID 35941662, 2022).
tumor (continued). "FGFR2 signalling promotes HER2 shedding through the metalloprotease ADAM10 and enhances HER2 signalling, HER2-dependent proliferation and tumour progression in mouse xenografts." (PMID 35193394, 2022). "The FGFR2 status of diffuse-type GC correlated with lymphatic invasion and MET and HER2 status, and inversely with PD-L1 expression in tumor-infiltrating immune cells." (PMID 35167603, 2022). "The results indicated that the RNA level of FGFR2 (p<0.05) and FGFR4 (p<0.001) was considerably higher in tumor tissues compared to the matched adjacent non-tumor tissues." (PMID 36147913, 2022). "We intend to estimate the contribution of FGFR2 to the epithelial–mesenchymal transition (EMT), tumor budding, and prognosis." (PMID 36143062, 2022). "It has been reported that in thyroid epithelial cells, FGFR2-IIIb reduces the expression of FGF7 and increases the ratio of FGF4/FGF7 and couples epithelial signalling with expansion of stomal to favour tumour growth." (PMID 35459137, 2022). "FGFR2 was also identified as a key driver of ILC using transposon mutagenesis in mouse mammary models, and despite initial sensitivity, tumours became resistant to FGFR inhibitor AZD4547." (PMID 33413533, 2021). "Specially, FGFR2 rearrangements (FGFR2/VTI1A and FGFR2/TACC2) were recurrently detected in 3.1% (2/64) PC GC tumor samples." (PMID 34551773, 2021). "The tumor from the youngest FGFR patient, F48, had FGFR2 alterations and a very aggressive course, resulting in rapid general status decline that precluded post-resection attempts to radio- and chemotherapy." (PMID 33853673, 2021). "Tumor cells expressed relatively high levels of EGFR, FGFR1, and FGFR2, while their corresponding ligands, such as COPA, GRN, HBEGF, FGF2, FGF7, and FGF18, were widely expressed in fibroblast cells." (PMID 34459128, 2021). "It has been reported that the levels of FGFR2 and FGFR3 strongly correlate with poor tumour differentiation." (PMID 33179425, 2021). "FGFR2 and CCNE1 gene amplifications were detected in single CTCs, tumor tissue, and ccfDNAs in one patient." (PMID 34178989, 2021). "We also used a tumor slice platform to demonstrate that a combination of FGFR inhibitor plus ICB mediated by PD‐1 and PD‐L1 effectively inhibits FGFR2‐induced tumorigenesis." (PMID 34514747, 2021). "Therefore, FGFR2 inhibition could profoundly affect tumor growth." (PMID 34514747, 2021). "We previously also reported that FGF9 bound and activated FGFR2 to promote the ERK1/2 and Rb/E2F1 pathways, and subsequently increased the expression of cyclins and CDKs to enhance cell proliferation and tumor growth both in vitro and in vivo." (PMID 33172093, 2020). "Together, targeting FGFR2 by small molecules inhibited YAP1 expression, suppressed tumor growth, and enhanced apoptosis in GC." (PMID 32934314, 2020). "Because we observed that Fgfr2 mRNA was significantly and consistently induced in VEGFR2-Fc–expressing tumors in the two tumor models, we focused on this receptor." (PMID 32076044, 2020). "Genetic alterations in FGFR1, FGFR2,and FGFR3 are reported in many tumor types and include all of the mechanismsdescribed leading to constitutive activation of the receptors or aberrantligand-dependent signaling through FGFRs." (PMID 32315352, 2020). "To examine the activation status of FGFR2 and the levels of FGF2 and FGFR2 in Mock and VEGFR2-Fc–expressing tumors, we conducted Western blot analysis of tumor lysates from tumors resected at a volume of ~500 mm3." (PMID 32076044, 2020). "Genomic heterogeneity of copy number alteration in tumour #1 and tumour #2 was observed in 7 (33%) of 21 patients including ERBB2 in two patients (patients 9 and 19), FGFR1 in two patients (patients 3 and 13), and FGFR2 in one patient (patient 4)." (PMID 31929516, 2020). "In a mouse model of PCa, ADAM9 was shown to play a critical role in tumor progression which was attributed to the ability of ADAM9 to cleave and release EGF and FGFR2 from cells." (PMID 32719332, 2020).
tumor (continued). "FGFR2, VEGFR2, CSF1R, and EGFR are tyrosine kinases that are constitutively activated in cancer cells to promote tumor progression and angiogenesis." (PMID 33488754, 2020). "Our results demonstrated that P5 significantly inhibited the cell proliferation in FGFR2‐dependent manner in DU145 cells and retarded tumor growth in DU145 xenograft model with negligible toxicity toward normal organs." (PMID 34766128, 2020). "Next, we examined in vivo tumor growth and tumor angiogenesis by inoculating various combinations of Mock, VEGFR2-Fc–expressing, or FGFR2-Fc–expressing tumor cells into syngeneic mice in Renca and B16F10 models." (PMID 32076044, 2020). "To examine the roles of the FGF signaling in in vivo tumor growth of VEGFR2-Fc–expressing tumors, we established Renca and B16F10 tumor cells overexpressing FGFR2-Fc (the extracellular domain of mouse FGFR2 fused to the Fc region of human IgG4)." (PMID 32076044, 2020). "Promoter methylation analysis of the region 2000bp upstream of the TSS of FGFR2 and ESRP1 revealed that most tumor samples from cohort #1 (datasets #3 and #4), cohorts #2, #3 and #4 were hypo/demethylated for both gene promoters." (PMID 31881796, 2019). "These pathways were all connected to tumor growth, and the PI3K/Akt signaling pathway (eight involved genes: CCND2, CDKN1B, CSF1, EFNA3, FGFR2, FGFR3, IL2RB, and ITGA9) ranked first among upregulated pathways (Enrichment Score = 3.159187)." (PMID 30755239, 2019). "FGFR2 and ESRP1 were co-amplified in up to 24% of TCGA tumors when tumor and normal samples were compared." (PMID 31881796, 2019). "Genes with a tumor suppressive role including FOXP1 and FGFR2 were downregulated in both cell groups." (PMID 31013771, 2019). "Forty-four unique fusions were identified in 40 (1.1%) of the 3,808 patients with circulating tumor DNA detected: RET (n = 6; 36% of all fusions detected), FGFR3 (n = 2; 27%), ALK (n = 10, 23%), NTRK1 (n = 3; 7%), ROS1 (n = 2; 5%), and FGFR2 (n = 1; 2%)." (PMID 33015522, 2019). "At this time, the patient underwent a repeat tumor biopsy and RNA profiling of his cancer using an NGS assay, OSU-SpARKFuse, which revealed a novel gene fusion involving FGFR2 (exons 1–16) and CLIP1 (exons 19–24)." (PMID 31371345, 2019). "Copy losses were also commonly observed for key tumor suppressors relevant to mCRPC biology, including GRHL2, ZFHX3, FGFR2, NCOR1, PHLPP1, and BRCA1." (PMID 31136607, 2019). "Reduction of tumor volume and weight, suppression of angiogenesis partly via FGF2/FGFR2 signaling pathway." (PMID 31402861, 2019). "In three cases where tumour tissue sequencing failed, amplifications in ERBB2, FGFR2, EGFR, and CCND1 were identified in ctDNA." (PMID 31137920, 2019). "When MSP was applied to tumour samples, a significant reduction of HOXD10, FGFR2 (P < 0.05), ITIH5 and RASAL3 (P < 0.001) promoter methylation was observed in DEC-treated mice." (PMID 30533020, 2018). "Conversely, FGFR2 overexpression increased CD44 expression and accelerated tumor growth in mice indicating the positive feedback mechanism in the regulation of CD44 and FGFR2 expression." (PMID 29747682, 2018). "BGJ398 is an orally available selective inhibitor of FGFR1, FGFR2, and FGFR3 that has been shown to potently inhibit tumor cell proliferation and tumor growth in various cancer models harboring genetic alterations in FGFR1/2/3." (PMID 30326563, 2018). "Treatment of a patient who carried FGFR2 F276C with an FGFR inhibitor resulted in significant and sustained tumor response with clinical benefit." (PMID 30761385, 2017). "In a comprehensive survey of gene fusions across different solid tumor histologies, the authors described a wide-ranging distribution of FGFR1, FGFR2, and FGFR3 fusions across 8 of 20 tumor types analyzed." (PMID 28030802, 2017). "In the five iCCA patients with FGFR2 fusions (BICC1 (n=2), KIAA1217, TACC1, CCDC6), two confirmed PRs and a SD (25% tumour reduction) of 24–41 weeks duration were observed." (PMID 28972963, 2017).